TLR2 (toll like receptor 2)
Diseases named in the same sentence as TLR2 in open-access papers (continued):
Sharing a sentence is not in itself a finding about the gene and the disease.
prostate carcinoma (15 papers, 2009 to 2026). A carcinoma that arises from epithelial cells of the prostate gland. "In prostate cancer, activation of TLR2, TLR4, and TLR9 stimulates tumor growth while activation of TLR3, TLR4, TLR5, and TLR7 suppress tumor development." (PMID 41601666, 2026). "While direct evidence in prostate cancer remains limited, these Gram-positive bacteria are typically recognized by TLR2 heterodimers, which detect lipoteichoic acids and lipoproteins, and are frequently associated with anticancer functions." (PMID 41601666, 2026). "Prostate cancer cell-derived exosomes upregulated CXCR4 expression in MDSCs through the activation of the TLR2/NF-κB, further facilitating the MDSCs’ migration into TME through CXCR4-CXCL12." (PMID 40443670, 2025). "Positively-identified TLR2 protein in all prostate cancer cells and TLR4 protein in PC3 and LNCaP by Western blotting was not accompanied by cell surface expression, as judged by flow cytometry." (PMID 24966802, 2014). "In conclusion, prostate cancer-derived exosomes could reinforce CXCR4 expression in MDSCs through the TLR2/NF-κB signalling pathway, eventually promoting migration of MDSCs into tumor microenvironment in a CXCR4-CXCL12 axis-dependent manner." (PMID 34659412, 2021). "Exosomes enriched with HSP70 were secreted from prostate cancer cells, inducing the engagement of TLR2 and phosphorylation of NF-κB, resulting in upregulating expression of CXCR4 in MDSCs and eventually leading to the accumulation of MDSCs into tumor microenvironment (TME)." (PMID 34659412, 2021). "Therefore we examined and compared expression of TLR1-10, MyD88 and CD14 and functional responsiveness to TLR-2 and 4 ligands in well-established prostate cancer cell lines." (PMID 24966802, 2014). "CRD domain of SP-D is known to interact with CD14, TLR-2, TLR-4, EGFR, and SIRPα that are reported to be present on prostate cancer cells and normal prostate tissues." (PMID 31355132, 2019). "We observed that TLR2, TLR6, and CD14 mRNA were expressed in prostate epithelial cell lines as well as in prostate cancer cell lines, and that these mRNAs were directly related to intracellular signaling upon stimulation with LTA in the human prostate." (PMID 26649771, 2015). "Based on the results of Western blot and flow cytometric analyses, we were then about to localize TLR2 and TLR4 expression in prostate cancer cells." (PMID 24966802, 2014). "Although the expression profile of multiple TLRs in cancer cells from different histologically origin has been investigated, few data are available on functional expression of TLR2 and TLR4 in prostate cancer cells." (PMID 24966802, 2014). "In this context, we evaluated functional consequences of TLR2 and TLR4-mediated activation in prostate cancer cells including proliferation, cell attachment, invasion and pro-inflammatory cytokine production." (PMID 24966802, 2014). "While the signaling mechanisms of TLRs are well characterized, they do not completely account for the contrasting effects observed in prostate cancer, where activation of certain receptors such as TLR3 suppresses tumor growth, whereas others like TLR2 enhance it." (PMID 41601666, 2026). "In this study, we demonstrated the recruitment of MDSCs can be promoted by exosomes derived from prostate cancer cells, which could upregulate chemokine (CXC motif) receptor 4 (CXCR4) via the TLR2/NF-κB signalling pathway." (PMID 34659412, 2021). "Our results showed that surface expression of TLR2 and TLR4 in prostate cancer cells is not affected by such treatments suggesting that TLR2 and TLR4 expressions are differentially regulated in a cell-specific fashion." (PMID 24966802, 2014). "In conclusion, new data were provided herein to support the hypothesis that exosomes secreted from prostate cancer could upregulate the expression of CXCR4 in MDSCs, putatively by increasing engagement of TLR2 and phosphorylation of NF-κB, resulting in MDSCs accumulation into tumor microenvironment." (PMID 34659412, 2021).
prostate carcinoma (continued). "The results clearly showed that such treatments could not up regulate surface expression of TLR2 and 4 in prostate cancer cell lines." (PMID 24966802, 2014).
cardiac hypertrophy (14 papers, 2012 to 2025). "Upon chronic pressure overload, TLR2 deficiency significantly tempered cardiac hypertrophy and preserved cardiac function in the vast majority of mice." (PMID 34769252, 2021). "In contrast, angiotensin-induced LV hypertrophy was similar between TLR2−/− and WT at 7 days, but TLR2 deficiency in bone marrow-derived cells reduced fibrosis and inflammation." (PMID 28835616, 2017). "Studies in vitro have implicated TLR2 signaling in T. cruzi-induced pathways leading to cardiac hypertrophy." (PMID 23355836, 2012). "After the detection of elevated TLR4 transcripts after 14 days of TAC, we assumed that TLR4 expression might increase early on and accounts for prolonged inflammation in TLR2 deficient mice, thereby promoting cardiac hypertrophy development." (PMID 27109115, 2016). "Tlr2 deficiency significantly enhanced cardiac hypertrophy after 14 and 28 days of TAC." (PMID 27109115, 2016). "On the contrary, Tlr2 deficiency impaired cardiac hypertrophy after TAC." (PMID 27109115, 2016). "However, in their model Tlr2 deficiency attenuated cardiac hypertrophy." (PMID 27109115, 2016). "Specifically, TLR2 has been shown to mediate cardiac hypertrophy and inflammation in mice induced by Ang II via the TLR2/MyD88/NF-κB signaling pathway." (PMID 40182777, 2025). "Although TLR2 has been shown to induce cardiac hypertrophy, several studies have suggested that TLR2 is required for cardiac protection." (PMID 37113698, 2023). "XIST promoted the progression of cardiac hypertrophy through competitively binding with miR-101 to enhance the expression of TLR2." (PMID 35990977, 2022). "TLR2−/− mice were protected against cardiac hypertrophy, fibrosis and dysfunction induced by sustained pressure overload, as compared to wild type mice." (PMID 32650372, 2020). "We sought to evaluate the role of TLR2 in cardiac hypertrophy, fibrosis and dysfunction in sustained pressure overload." (PMID 28835616, 2017). "The extent of cardiac hypertrophy was increased in Tlr2−/− versus Tlr2+/+ mice as demonstrated by a 22.1 % higher HW/TL ratio (p < 0.01) and 19.2 % elevated LVW/TL ratio (not significant)." (PMID 27109115, 2016). "Our findings suggest that genetic disruption of Tlr2 cannot prevent cardiac hypertrophy in a model of hemodynamic overload." (PMID 27109115, 2016). "A recent study has suggested that lncRNA X-inactive specific transcripts (XIST) could induce cardiac hypertrophy by targeting miR-101 and increasing TLR2 levels." (PMID 37113698, 2023). "Besides, TLR2 is involved in renal ischemia/reperfusion (I/R)-induced cardiac hypertrophy by regulating the systemic inflammatory profile and NF-κB activation." (PMID 37113698, 2023). "Besides, studies have demonstrated that heat shock proteins (HSPs), such as HSP60 and HSP70, induced cardiac hypertrophy by activating NF-κB through the TLR2/MyD88-dependent pathway in Dox-induced animal models." (PMID 37113698, 2023). "Therefore, the role of TLR2 in cardiac hypertrophy is destructive or protective, depending on the etiology and disease stage." (PMID 37113698, 2023). "The role of TLR2 in cardiac hypertrophy is however conflicting in the literature." (PMID 28835616, 2017). "TLR2 deficiency does not affect hypertrophy but reduces fibrosis and protects from cardiac systolic and diastolic dysfunction." (PMID 28835616, 2017). "Our data suggest, that TLR2 signaling may preserve cardiac function and limit cardiac hypertrophy in a murine model of pressure overload." (PMID 27109115, 2016). "Future studies need to elucidate whether estrogen-dependent TLR2 transcription occurs upon aortic constriction in female mice, and whether this contributes to the attenuated development of cardiac hypertrophy." (PMID 27109115, 2016). "We aimed to elucidate whether gender interferes with the TLR2 dependent development of cardiac hypertrophy." (PMID 27109115, 2016).
cardiac hypertrophy (continued). "However, TLR2 deletion in a hypertrophy model (TAC) revealed that TLR2 is required for adaptive cardiac hypertrophy through IL-1β upregulation via NF-κB activation." (PMID 24611063, 2014). "We aimed to clarify, whether TLR2 contributes to the development of cardiac hypertrophy." (PMID 27109115, 2016). "TLR2/NF-κB/IL-1β signaling is essential for activating the IGF-1/PI3K/Akt pathway and leads to adaptive cardiac hypertrophy during pressure overload." (PMID 37113698, 2023). "In the mice model of cardiac hypertrophy, the lncRNA-XIST was verified to be a necessary regulator of the formation of cardiac hypertrophy via the miR-101/TLR2 axis in both in vivo and in vitro assays." (PMID 36091364, 2022). "Therefore, we investigated whether TLR2 is also involved in the development of cardiac hypertrophy." (PMID 27109115, 2016). "Finally, adenoviral overexpression of dominant-negative MyD88, a common adaptor of TLR2 and TLR4, significantly reduced cardiac hypertrophy and cardiac fibrosis in an aortic constriction model improving cardiac function." (PMID 24611063, 2014). "Besides, CaMKIIδB silencing prevents cardiac hypertrophy independent of an inflammatory response by inhibiting the complement system and TLR2/4 NF-kB signaling." (PMID 37113698, 2023). "Moreover, severe injury such as cardiac hypertrophy is displayed, which indicates the involvement of several DRGs of IL6, LUM, LRG1, PLG, with other molecules such as Alpha actinin, PDGF, Tgf beta, and TLR2 and TLR4." (PMID 32753925, 2020). "In the chronic settings, the benefits of anti-apoptotic effects attributed to purified cruzipain and BK2R signaling may be offset by the up-regulation of BK1R, a pathway that may synergize with TLR2 and ETAR, hence fueling inflammatory edema and cardiac hypertrophy in chronically infected patients." (PMID 23355836, 2012).
cutaneous leishmaniasis (14 papers, 2010 to 2023). Leishmaniasis affecting the skin. "Nonetheless, and similar to TLR2, milder forms of human cutaneous leishmaniasis due to L. braziliensis are associated with higher expression of TLR4." (PMID 31806038, 2019). "Previous studies reported that inhibition of TLR2 and 4 attenuates inflammatory response and parasite burden in cutaneous leishmaniasis." (PMID 37885890, 2023). "TLR2 plays critical role in the control of cutaneous leishmaniasis while its absence augments TH2 responses resulting in exacerbated infection." (PMID 35119120, 2022). "In contrast, blockage of both TLR2 and TLR4 suppressed the proinflammatory response and parasite load in monocytes/macrophages collected from human cutaneous leishmaniasis caused by Leishmania braziliensis." (PMID 36190414, 2022). "In human cutaneous leishmaniasis the up-regulation of TLR2/TLR4 expression in monocytes correlates with disease outcome, their up-regulation expression by macrophages and monocytes is related to healing lesions by increasing ROS and NO production." (PMID 34745100, 2021). "A higher expression of TLR-2 was identified in monocytes from patients with cutaneous leishmaniasis (CL)." (PMID 33194814, 2020). "TLR4 and TLR2 is expressed in lesions of cutaneous leishmaniasis and TLR2 in blood cells of VL patients, suggesting that these signaling molecules are involved in Leishmania infections." (PMID 26814478, 2016). "This is the first study, to our knowledge, to attribute a clear role for TLR2 in the control of infection in cutaneous leishmaniasis." (PMID 27716391, 2016). "In summary, a role for TLR2 in controlling cutaneous leishmaniasis disease severity has been demonstrated in vivo." (PMID 27716391, 2016). "It would be interesting to further explore the role of the skin microbiota in relation to TLR2 activation in cutaneous leishmaniasis in mice." (PMID 27716391, 2016). "The role of TLR2, 1, 6 and 4 in lesion development in cutaneous leishmaniasis was explored by carrying out infection experiments using mice specifically deficient in these TLRs." (PMID 27716391, 2016). "Collectively, our studies revealed that up-regulated TLR2/4 expression and TNF production by intermediate/inflammatory subsets of monocytes from patients correlates with detrimental outcome of cutaneous leishmaniasis." (PMID 31119102, 2019). "Our data on TLRs in granulomas in patients with cutaneous leishmaniasis are in accordance with the literature, where TLR9 and TLR2 have been reported." (PMID 25397678, 2014).
experimental autoimmune encephalomyelitis (14 papers, 2011 to 2024). An autoimmune demyelinating disease of the central nervous system that is produced experimentally in animals by the injection of homogenized brain or spinal cord in Freund's adjuvant. "It has been previously reported that TLR-4, TLR-2, and adaptor MyD88 are directly involved in modulating the regulatory function of B cells in a murine model of experimental autoimmune encephalomyelitis (EAE)." (PMID 34867973, 2021). "While most MS therapeutics target adaptive immunity, we recently reported that reducing TLR2 signaling in innate immune cells by inducing TLR2 tolerance attenuates adoptively transferred experimental autoimmune encephalomyelitis." (PMID 31351476, 2019). "The TLR2 signal induced by zymosan results in the active suppression of experimental autoimmune encephalomyelitis (EAE)." (PMID 21533081, 2011). "Immunosuppressive properties of B cells, especially the production of IL-10 in experimental autoimmune encephalomyelitis (EAE) mice model is dependent on toll-like receptor-2 (TLR-2), toll-like receptor-4 (TLR-4)and myeloid differentiation primary response 88 (MyD88) signaling." (PMID 34867973, 2021). "It was previously shown that toll-like receptor (TLR)-2 signaling plays a key role in the murine experimental autoimmune encephalomyelitis (EAE) model of MS, and that TLR2-stimulation of regulatory T cells (Tregs) promotes their conversion to T helper 17 (Th17) cells." (PMID 29593720, 2018). "Similarly, in a mouse model of experimental autoimmune encephalomyelitis, oleanolic acid acetate suppressed the production of pro-inflammatory cytokines IL-1β, IL-6, INF-γ, and TNF-α by regulating toll-like receptor 2 (TLR2) signaling." (PMID 34360922, 2021). "In the murine model of MS, experimental autoimmune encephalomyelitis (EAE), the lack of TLR2 in CD4+ T cells was shown to ameliorate EAE, while inducing TLR2 tolerance via low-levels of a microbiome-derived TLR2 agonist resulted in amelioration of EAE." (PMID 32993761, 2020).
leishmaniasis (14 papers, 2010 to 2024). Infectious disease that is transmitted through the bite of hematophagous female phlebotomine sand flies. "Murine models of leishmaniasis have linked various TLRs (TLR2, TLR3, TLR4 and TLR9) with enhanced IFN-γ and IL-12 production and parasite control." (PMID 25397678, 2014). "Involvement of TLRs, primarily TLR2 and 4, is known to elicit differentiation of T helper (Th-1) cells that are engaged in significant mitigation of leishmaniasis." (PMID 38035118, 2023). "TLR2 is inferably the most significant toll‐like receptor to Leishmania infection because it is most expressed in active stage of leishmaniasis as compared to other TLRs." (PMID 35119120, 2022). "NK cells are among the first to produce IFN-γ and TNF-α in response to pathogen presence and in leishmaniasis, these cells can become activated after the binding of TLR2 to Leishmania LPG." (PMID 27031998, 2016). "Hence, in addition to the role of TLR2 in innate immune response, it also regulates adaptive immune response towards leishmaniasis." (PMID 35119120, 2022). "Most studies of TLRs in leishmaniasis have been done in the murine models, where expression of TLR2, TLR4, TLR7, TLR8 and TLR9 have been analyzed and related to disease outcome, together with other contributing factors such as Leishmania species and genetic background." (PMID 25397678, 2014). "Several reports have shown that the blockade of TLR2 and TLR4 attenuates inflammation in various forms of leishmaniasis." (PMID 37033485, 2023). "TLR2 and TLR3), which are popular targets in many diseases including leishmaniasis." (PMID 26660865, 2015). "As far as we are aware, despite the importance of mammalian TLRs in leishmaniasis in general, there have been no studies concerning TLR2 in CVL." (PMID 22140456, 2011). "In diffuse cutaneous (DCL) leishmaniasis that is characterized by uncontrolled parasite dissemination and poor production of IFN-γ patients showed reduced NK cell numbers that down-regulated TLR2, TLR1 and TLR6 expression as well as reduced cytokine production, as compared to CL patients." (PMID 34691019, 2021).
myocardial ischemia (14 papers, 2012 to 2022). A disorder of cardiac function caused by insufficient blood flow to the muscle tissue of the heart. "It appears that inhibition of the activity of TLR2 signaling pathway improves the cardiac functional outcome after myocardial ischemia." (PMID 35493479, 2022). "TLR2 is a member of the TLRs family which plays an important role in myocardial ischemia–reperfusion injury." (PMID 32394311, 2020). "TLR-2 signaling is involved in myocardial ischemia/reperfusion injury and in coronary artery endothelial dysfunction with impaired vessel relaxation induced by transient ischemia." (PMID 24971143, 2014). "Whereas TLR4 has shown to play a detrimental role in myocardial ischemia/reperfusion (I/R) injury, the effect elicited by TLR2 activation remains controversial." (PMID 25566092, 2014). "The results from the present study identify a relation between HMGB1 and TLR2-signalling in myocardial ischemia and reperfusion." (PMID 24371373, 2013). "Genetic or pharmacological ablation of toll-like receptor 2 (TLR2) protects against myocardial ischemia/reperfusion injury (MI/R)." (PMID 24371373, 2013). "We and others have shown that antibody blockade, pharmacological preconditioning, or genetic ablation of toll-like receptor 2 (TLR2) signalling is protective in a mouse model of myocardial ischemia and reperfusion (MI/R)." (PMID 24371373, 2013). "However, the molecular mechanism of TLR2 in myocardial ischemia reperfusion remains to be investigated." (PMID 32394311, 2020). "Furthermore, research in mice models revealed that TLR2 signaling triggers fatal arrhythmias upon myocardial ischemia-reperfusion." (PMID 29077004, 2017). "Besides the known involvement of its receptor RAGE, we here provide evidence for a role of TLR2 in mediating effects of endogenous HMGB1 released during acute myocardial ischemia and reperfusion." (PMID 24371373, 2013). "For instance, in myocardial ischemia/reperfusion injury, RP105 plays a cardioprotective role by modulating both TLR2/TLR4 signaling pathways." (PMID 36136452, 2022). "Smaller infarctions and less inflammation has also been observed in mice subjected to myocardial ischemia-reperfusion and treated with TLR2 or TLR4 antagonists (anti-TLR2 antibody and Eritoran, respectively)." (PMID 29077004, 2017). "C57BL/6 wild-type (WT) or TLR2−/−-mice were injected with vehicle, HMGB1, or HMGB1 BoxA one hour before myocardial ischemia (30 min) and reperfusion (24 hrs)." (PMID 24371373, 2013). "Taken together, TLR2, TLR9, TNF-α and IL-10 were still elevated above control at the onset of cardiac ischemia." (PMID 23929312, 2013). "This redox modification, which has been suggested to be dependent on Toll-like receptor 2 (TLR2) activation, might be important under pathological situations, such as during myocardial ischemia/reperfusion." (PMID 33922534, 2021).